SENP3 (SUMO specific peptidase 3)
Diseases named in the same sentence as SENP3 in open-access papers (continued):
Sharing a sentence is not in itself a finding about the gene and the disease.
tumor (continued). "Kaplan–Meier analysis demonstrated that higher SENP3 levels in tumour tissues were obviously correlated with the enhanced overall survival (OS) rates in BLCA, CHOL, LIHC and SARC cancers." (PMID 35356800, 2022). "Consistently, increased proliferation and decreased apoptosis were observed in post‐4‐week tumor tissues from Senp3 cKO mice, as evidenced by immunohistochemical (IHC) staining of Ki67 and cleaved caspase‐3, respectively." (PMID 33932085, 2022). "In this study, we showed that the mitotic SENP3 phosphorylation modulates host anti-tumor immunity by regulating MN-induced cGAS-STING signaling." (PMID 35869062, 2022). "Moreover, SENP3 may also promote cancer progression by regulating macrophage polarization, and high SENP3 levels are associated with more advanced tumor grades and metastasis as well as poor survival outcomes, meaning that SENP3 may play a role in tumorigenesis and progression." (PMID 36698419, 2022). "We did these observations by using SENP3 phosphorylation mutant tumor cell line in vitro or tumor mice model." (PMID 35869062, 2022). "It is conceivable that mitotic SENP3 activation would be a critical target for chemotherapy-induced anti-tumor immunity." (PMID 35869062, 2022). "Next, we evaluated the correlation between SENP3 levels in M2 macrophages and clinical outcomes, including tumor stage, clinical tumor, lymph node, metastasis (TNM) classification, and lymphatic metastasis." (PMID 33932085, 2022). "Meanwhile, we also observed that the reduction of cGAS expression reversed SENP3–9A-mediated inhibition of tumor growth in C57BL/6 mice." (PMID 35869062, 2022). "In tumor cells, the stability of SENP3 protein increases and accumulates in the nucleoplasm by altering redox state under hypoxia, oxidative stress and other stimuli." (PMID 35484132, 2022). "Our results showed that the SENP3 knockdown tumour cells were most sensitive to CPT, a TOP1 inhibitor that induced DNA damage in and around the cell cycle but not as a DNA synthesis inhibitor." (PMID 35356800, 2022). "Collectively, SENP3 appears to act as a specific regulator for M2 polarization for various types of tumor." (PMID 33932085, 2022). "SENP3 depletion in DCs promotes tumor growth by suppressing antitumor immune response by dampening STING-dependent type-I interferon (IFN) signaling." (PMID 35887358, 2022). "In this study, we show that mitotic SENP3 activation in tumor cells inhibits the tumor growth in immune-competent C57BL/6 mouse model, which is the opposite of what was observed in tumor-bearing nude mice model." (PMID 35869062, 2022). "Knocking down of SENP3 impairs DNA repair efficiency, and such tumour cells become hypersensitive to radiotherapy and chemotherapy." (PMID 35356800, 2022). "If mitotic SENP3 phosphorylation can be used as a marker of anti-tumor immunity, it will be applied as an indicator to determine suitable patients for using anti-tumor immunotherapy." (PMID 35869062, 2022). "A similar analysis of CD45+ immune cells from the draining lymph nodes near the tumor also showed that the population of CD8+ T cells but not CD4+ T cells were much more in the SENP3–9A tumor model than in the SENP3-WT tumor model." (PMID 35869062, 2022). "In this study, we demonstrate that mitotic SENP3 activation can promote innate immune response in tumor cells, which induces host anti-tumor immunity to suppress tumor growth." (PMID 35869062, 2022). "PANC-1 cells with intact SENP3 exhibited rapid tumor growth; in contrast, SENP3 depletion markedly inhibited tumor growth." (PMID 35484132, 2022).
tumor (continued). "High levels of ROS following TCR and CD28 stimulation enhance Treg cell-mediated tumor immunosuppression and attenuate anti-tumor T cell responses by stabilizing SENP3." (PMID 33732706, 2021). "The IHC analysis of ARID1A, CSMD1, and SENP3 proteins showed that the expression level of all the three genes was significantly different between tumor and paracarcinoma tissues (P < 0.05)." (PMID 33558447, 2021). "Herein, we focused on ARID1A, CSMD1, and SENP3 during tissue microarray analysis of 180 HCC samples paired with tumor and paracarcinoma tissues as a replication population." (PMID 33558447, 2021). "A previous study indicated that the expression level of SENP3 was significantly increased and is associated with pathological characteristics in OSCC tissues compared to normal mucosa tissue adjacent to the tumor." (PMID 33192553, 2020). "We observed that tumor-infiltrating Treg cells exhibited higher level of ROS and SENP3 than did the splenic Treg cells in wild-type mice." (PMID 30089837, 2018). "Compared to the Senp3+/+Foxp3-Cre mice, the Senp3fl/flFoxp3-Cre mice displayed a profound reduction in tumor size and in the frequency of tumor-infiltrating Treg cells." (PMID 30089837, 2018). "We found that NAC treatment significantly decreased the frequency of tumor-infiltrating Treg cells in Senp3+/+Foxp3-Cre mice." (PMID 30089837, 2018). "The expression of SENP3 was higher in OSCC tissues than that in the normal mucosa adjacent to the tumor, and a modest increase in reactive oxygen species (ROS) regulated SENP3 stability and localization." (PMID 23467634, 2013). "Therefore, we focused on the process that tumor-intrinsic SENP3 promotes macrophage infiltration by augmenting CCL20 secretion." (PMID 39755756, 2025). "In summary, these findings demonstrate the tumor-promoting effect of SENP3 on HCC cells in vitro." (PMID 39755756, 2025). "Additionally, we explored the mechanism of tumor-intrinsic SENP3-mediated immune escape using cytokine microarray." (PMID 39755756, 2025). "Furthermore, we revealed that the combination of SENP3 knockdown with anti-PD-1 treatment reduced HCC tumor growth more effectively than either anti-PD1 therapy or SENP3 inhibition alone." (PMID 39755756, 2025). "Importantly, a reduction in tumor-associated macrophages (TAM) infiltration and an increase in CD8 + T cells and NK cells were observed in the SENP3 knockdown group; whereas SENP3 overexpression exerted the opposite effect." (PMID 39755756, 2025). "Our findings revealed that both elevated and reduced expression levels of UBC9, SENP1, SENP3, SENP5, and SENP7 may be associated with poor prognosis across various tumor types." (PMID 41268439, 2025). "Furthermore, reported in various cancers except for EAC as relevant to activating PI3K-Akt signaling pathway or promoting tumor through SENP3/SP1/SQLE axis, SERPINH1 was also identified as a key gene in EAC in the current study." (PMID 40872572, 2025). "All these data indicate that SENP3 is essential for ESCC-associated macrophages, and its increased activity could be a promising strategy for tumor immunotherapy." (PMID 39123188, 2024). "A previous study reported that the activation of SENP3 in tumor cells could be coupled with the cGAS signaling, synergistically promoting host anti-tumor immune responses." (PMID 39314848, 2024). "To further verify the localization of SENP3, we performed multiple immunofluorescence staining, and the results showed that SENP3 was significantly upregulated in CD68-positive cells in tumor tissues compared with normal tissues, which is a common marker of macrophages." (PMID 39123188, 2024). "Furthermore, SENP3 activity enhances anti-tumor immune responses, a mechanism that is facilitated by cGAS in mice." (PMID 38139802, 2023). "We analyze the relationship between SENP3 expression level and tumor patient prognosis." (PMID 35869062, 2022). "We next addressed how mitotic SENP3 activation in tumor cells promotes host anti-tumor immunity." (PMID 35869062, 2022).
tumor (continued). "SENP3 knockdown can inhibit tumor proliferation, invasion, and migration." (PMID 36698419, 2022). "We confirmed that cGAS signaling mediates the mitotic SENP3 activation-induced anti-tumor immunity." (PMID 35869062, 2022). "Given that TAM is well‐known to promote cancer progression, these results also suggest that Senp3 might regulate TAM function in tumor niches and further affect the crosstalk between TAM and cancer cells." (PMID 33932085, 2022). "Mitotic SENP3 activation has an obvious anti-tumor effect in the immune-competent mouse models." (PMID 35869062, 2022). "Moreover, ROS can induce the accumulation of SUMO-specific protease 3 (SENP3), which is related to the anti-tumor immunosuppression of Treg to T cells." (PMID 35832074, 2022). "Indeed, we compared the activation of cGAS-STING signaling in both SENP3-WT- and SENP3–9A tumor cells." (PMID 35869062, 2022). "We also observed that anti-CD8 antibodies can increase tumor growth in SENP3-WT tumors, suggesting that such CD8+ T cells may have broad anti-tumor effects but not only response for SENP3–9A-mediated anti-tumor immunity." (PMID 35869062, 2022). "Overexpression of SENP3 accelerated tumor growth compared with control group." (PMID 36227136, 2022). "Although we have no direct evidence to support for the micronuclei as essential for mitotic SENP3-activated innate immune response, we identify cGAS as an essential regulator for the mitotic SENP3-activated innate immune response in tumor cells via promoting micronucleus formation." (PMID 35869062, 2022). "Taken together, SENP3 in macrophages might be an important regulator in TNBC or more advanced tumor." (PMID 33932085, 2022). "Considering SENP3–9A tumor growing in immune-competent mice, we reasoned that SENP3–9A in tumor cells could induce host anti-tumor immunity to inhibit tumor growth in immune-competent mice." (PMID 35869062, 2022). "We further examined whether other immune cells were affected by SENP3 deficiency in macrophages, including myeloid‐derived suppressor cells (MDSCs), CD4+ and CD8+ T cells isolated from tumor tissues, spleen, and tumor‐draining lymph nodes." (PMID 33932085, 2022). "In addition, platelet/endothelial cell adhesion molecule 1 (Pecam)/CD31 staining indicated enhanced tumor angiogenesis in tumors from Senp3 cKO mice." (PMID 33932085, 2022). "If we have such anti-SENP3 phosphorylation antibody suitable for immunostaining patient tumor samples, we can screen mitotic SENP3 phosphorylation status in patient tumor samples and determine whether it is related to anti-tumor immunity in patients." (PMID 35869062, 2022). "SENP3 downregulation depends on the hyper-SUMOylation of Akt1 followed by its hyper-phosphorylation and activation which is responsible for M2 polarization in the tumor microenvironment and for tumor progression." (PMID 35465332, 2022). "Moreover, in a subcutaneous injection with Py8119 cells, besides higher tumor weight, we observed more spontaneous lung metastatic sites in Senp3 cKO mice 4 weeks after transplantation." (PMID 33932085, 2022). "We hypothesized that mitotic SENP3 activation would enhance the innate immune response in tumor cells to induce host anti-tumor immunity." (PMID 35869062, 2022). "Although SENP3 was explored as a regulator of macrophage polarization in our study, how SENP3 responds to the cytokines in the tumor microenvironment still remains unclear." (PMID 33932085, 2022). "We would like to further determine whether activating mitotic SENP3 in tumor cells could perform the same in immune-competent mice as in nude mice." (PMID 35869062, 2022). "Consistently, IHC revealed more CD206+ cells in the tumor tissues from Senp3 cKO mice." (PMID 33932085, 2022). "SENP3 has been viewed as a stress sensor, given degradation inhibition and rapid accumulation resulting from the oxidative modification upon secondary oxidative stress in multiple normal and tumor cell lines." (PMID 33932085, 2022).
tumor (continued). "Due to mitotic SENP3 activation in tumor cells play a critical role in regulation of host anti-tumor immunity, we assume the high SENP3 expression may represent high SENP3 activity including in mitosis of tumor cells in these patients." (PMID 35869062, 2022). "To determine further whether the effect of SENP3 loss on macrophage polarization requires the presence of tumor cells, we generated primary BMDM from WT and Senp3 cKO mice and cultured them in conditioned media (CM) from Py8119 cells." (PMID 33932085, 2022). "Similarly, conditional Bach2 or Senp3 ablation in Treg cells leads to enhanced anti-tumor immunity and delayed progression of transplanted colon cancer and melanoma, respectively, demonstrating a Treg-cell-intrinsic function of Bach2 in cancer." (PMID 33143070, 2020). "In contrast, the B6.SJL mice injected with SENP3-deficient Treg cells treated with or without NAC displayed no apparent difference in tumor growth." (PMID 30089837, 2018). "To further assess whether SENP3 is involved the regulation of Treg cell-mediated tumor immunosuppression by ROS, we carried out a side-by-side comparison using tumor-bearing Senp3+/+Foxp3-Cre, Senp3fl/flFoxp3-Cre, and Rag1−/− mice treated with NAC." (PMID 30089837, 2018). "Notably, SENP3 accumulation triggered by reactive oxygen species (ROS) is involved in Treg cell-mediated tumor immunosuppression." (PMID 30089837, 2018). "In addition, SENP3 deletion reduced tumor growth in two HCC models." (PMID 39755756, 2025). "Interestingly, specific SENP3 inhibition in macrophages promoted tumor growth." (PMID 39123188, 2024). "However, whether and how SUMOylation or SENP3 manipulates M2 polarization is poorly understood, especially during tumor progression." (PMID 33932085, 2022). "However, whether SENP3 affects tumor development through directly regulating protein deSUMOylation is unclear." (PMID 35484132, 2022). "Therefore, our study suggests that macrophages could be educated and polarized to M2 through fine‐tuning Akt1 SUMOylation by SENP3 in response to tumor environment factors." (PMID 33932085, 2022). "Thus, SENP3-mediated NFATc3 deSUMOylation could increase NFATc3 nuclear occupancy and activate NFATc3 signaling for promoting tumor cell proliferation and invasion under hypoxia." (PMID 35484132, 2022). "Indeed, tumor-bearing Senp3+/+Foxp3-Cre mice treated with NAC displayed reduced tumor size." (PMID 30089837, 2018). "SENP3-mediated deSUMOylation modulates NFATc3, which is involved in PDAC tumor progression in hypoxic conditions." (PMID 39822413, 2024). "Our results highlight that SENP3-mediated deSUMOylation acts as an essential modulator of NFATc3, which is instrumental in PDAC tumor progression under hypoxia." (PMID 35484132, 2022). "The colony formation assay showed that SENP3–9A-MC38 cells grown more colonies than SENP3-WT-MC38 did, a consistent phenotype shown in human tumor cell U2OS." (PMID 35869062, 2022). "Surprisingly, the expression of CSMD1 and SENP3 was significantly decreased in tumor tissues (P-value < 0.05, 3D for CSMD1, 3F for SENP3)." (PMID 33558447, 2021). "Specifically, Carma1, Rel, Nrp1, Ezh2, Senp3, and Ikzf2-null Treg all produce appreciable amounts of IFNγ and/or TNF in the tumor microenvironment." (PMID 33143070, 2020). "Our results identify the role of SENP3-triggered BACH2 deSUMOylation in the cross-talk between ROS and Treg cell-mediated tumor immunosuppression." (PMID 30089837, 2018).
tumor (continued). "To study whether SENP3-mediated deSUMOylation affects HCC immune microenvironment, we established subcutaneous tumor models in immunocompetent and immunodeficient mice, respectively." (PMID 39755756, 2025). "Indeed, we found that anti-PD1 slightly inhibited the tumor growth in Hepa1-6 NC groups, while anti-PD1 combined with SENP3 knockdown significantly suppressed HCC tumor growth." (PMID 39755756, 2025). "Eventually, the SENP3 ablation xenografts had a significantly diminished tumor weight and size without influencing the weight of various groups." (PMID 39623295, 2024). "However, we generated MC38 cell subcutaneous tumor model in C57BL/6 mice and showed that the SENP3–9A MC38 tumors grown much smaller than the SENP3-WT MC38 tumors in C57BL/6 mice." (PMID 35869062, 2022). "Quantitative analysis demonstrated that the micronucleus positive cells were up to ~50% among SENP3–9A-U2OS cells as compared to ~20% positive cells among SENP3-WT-U2OS cells, confirming that SENP3–9A expression increases the formation of micronuclei in tumor cells." (PMID 35869062, 2022). "The limitation is that we did not validate these results in tumor patients, as without suitable anti-SENP3 phosphorylation antibodies for immunostaining." (PMID 35869062, 2022). "Besides, the M2 polarization of TAM at the tumor site was not affected regardless of SENP3 knockdown or overexpression." (PMID 39755756, 2025). "Interestingly, further study unveiled the unique effect of SENP3 in modulating tumor invasion but not in cell proliferation, which was largely reported to be regulated by the SUMO pathway." (PMID 37188742, 2023). "Thus, we wondered whether Sp1 can be conjugated with SUMO2/3 and be a substrate of SENP3, as we have previously shown that the protein level of SENP3, a SUMO2/3 specific protease, is increased in tumor tissues and under various stress conditions." (PMID 26511642, 2016). "Interestingly, when patients were stratified by the expression of SENP3, DKC1 lost its role as an indicator for poor outcomes among patients with lower expression of SENP3, implicating that SUMOylated DKC1 might exert a more robust pro-tumor effect." (PMID 37188742, 2023). "The absence of SENP3 expression in DCs abrogates IFN-I responses, and the low frequency of IFN-γ-expressing CD4+ and CD8+ effector T cells in the tumor and draining lymphoid nodes results in poor anti-tumor activity." (PMID 38280996, 2024). "Interestingly, the prognostic value of DKC1 was not significant in patients with low expression of SENP3, indicating that SUMOylation statue plays an important role in the DKC1-mediated pro-tumor effect." (PMID 37188742, 2023).